CRP (C-reactive protein)
Diseases named in the same sentence as CRP in open-access papers (continued):
Sharing a sentence is not in itself a finding about the gene and the disease.
influenza (continued). "This review describe current evidence and provide recommendations about the use of biomarkers in influenza and SARS-CoV-2 pneumonia, focusing mainly on procalcitonin (PCT) and C-reactive protein (CRP)." (PMID 36671362, 2023). "Random forest analysis showed that PCT, DD, CRP, respiratory rate, SpO2, albumin, AST/SGOT, calcium, influenza-like symptoms, and ALT/SGPT are the most important variables to predict the need for ICU." (PMID 34496940, 2021). "But severe influenza patients with aspergillosis mostly belonged to the H1N1 category and accompanied with higher inflammatory level represented by CRP and IL-6." (PMID 33537328, 2020). "Decreases average level of CRP and IFN-γ in serum of the influenza patients, and decreases inflammatory response." (PMID 32848729, 2020). "In this regard, the comparison of influenza and CAP patients revealed only a weak discriminative potential of neopterin, in contrast to CRP." (PMID 31489989, 2019). "Furthermore, as this study focuses on H1N1 influenza, the association between CRP levels and severity of infection may not be extended to other type of influenza strains and infections." (PMID 30288556, 2019). "The concentrations of CRP, Hp, and SAA were generally higher in pigs with clinical course of influenza." (PMID 24734294, 2014). "The thresholds used for CRP (>60 mg/dL) and PCT (>2 ng/mL) were selected as markers of potential severe inflammation based on clinical practice rather than validated prognostic cut-offs for bacterial co-infection in influenza." (PMID 41598308, 2026). "Multivariable analysis revealed that lack of influenza vaccination, antibiotic usage, sore throat, myalgia, gastrointestinal symptoms, elevated C-reactive protein levels, and increased frequency of medical visits were independent risk factors (P < 0.05)." (PMID 42038221, 2026). "It was [previously] a clinical decision...Now we’ve got the COVID test, influenza, maybe RSV added to that... and then we do a CRP." (PMID 41009893, 2025). "In most instances, other rapid tests, such as those for influenza or CRP, are not available in this setting." (PMID 41560722, 2025). "Another systematic review concluded that the two infections do not cause significantly different variations in CRP and procalcitonin values, but found a contrasting increase in LDH values for influenza infections in children." (PMID 40430211, 2025). "If influenza vaccination impacts RMR but RMR peaks at a different time than CRP, the RMR response would not have been captured within our study design." (PMID 38100425, 2023). "Low PCT values, particularly when combined with low CRP levels, suggest the absence of bacterial infection, either alone or in combination with influenza." (PMID 35055399, 2022). "While, C-reactive protein levels have not been well-examined in patients with seasonal influenza, several small studies identified higher levels in patients with severe disease during the 2009 H1N1 pandemic." (PMID 34673782, 2021). "A total of 4173 patients with influenza infection were enrolled at 184 ICUs between the study period; 2262 patients were excluded because of missing values in PCT and CRP at admission or in mortality, and 303 were excluded because of the non-respiratory source of infection." (PMID 33810263, 2021). "We therefore do not recommend the use of CRP for predicting recovery time of ILI, or as a tool for use in addition to established influenza risk factors for evaluating which patients should be prescribed oseltamivir treatment or not for ILI." (PMID 34850657, 2021). "By week 51, there were 28,281 CRP confirmed H1N1pdm09 cases, 112,415 Influenza B cases, and 139,655 Influenza A not subtyped in the Americas, but at the same time, there were 13,351,225 SARS-CoV-2 confirmed cases." (PMID 33557082, 2021).
influenza (continued). "The majority of the studies examining the initial levels of CRP in H1N1 influenza suggest that they significantly increase in patients who develop severe complications of influenza compared to those with no severe disease outcome." (PMID 30288556, 2019). "Also, neopterin levels can discriminate between influenza infection, healthy controls, and CAP; however, CRP and WBC revealed higher AUC." (PMID 31489989, 2019). "In conclusion, the present study provides evidence that CRP levels upon diagnosis is significantly higher (on average) in patients who develop severe complications of influenza compared to those who present a non-severe course of the disease." (PMID 30288556, 2019). "When influenza A and B were removed from viral (n = 25) and mixed (n = 15) groups, PCT and CRP levels showed significantly higher levels in mixed CAP compared to viral CAP without influenza (p = 0.019 and 0.046, respectively)." (PMID 25073709, 2014). "We included mixed viral-bacterial CAP not restricted to the influenza virus in a homogeneous adult group of patients, and both PCT and CRP were different in viral CAP without influenza than mixed CAP without influenza." (PMID 25073709, 2014). "This study aims to describe the demographic characteristics and outcomes of obese patients with severe influenza infection during the first A(H1N1)pdm09 wave in Australia; and to determine the relationship between BMI (as a marker of obesity), CRP and viral pneumonitis in severe influenza infection." (PMID 23418448, 2013). "Elevated CRP levels are suggestive of a bacterial infection but may be observed in patients with certain viral strains (e.g., adenovirus and influenza) and non-infectious conditions." (PMID 40150663, 2025). "PCT, but not CRP, was different between influenza-positive and influenza-negative individuals (P = 0.03), but median values were the same for both groups, with overlapping confidence intervals (CI) (influenza-negative, 0.1 [95% CI 0.1 to 0.1]; influenza-positive, 0.1 [0.1 to 0.18])." (PMID 34817224, 2021). "Combining influenza tests with other POCTs, such as C-reactive protein, may help rule out bacterial co-infection to reduce antibiotic prescribing rate in primary care settings." (PMID 32172369, 2020). "We also found a serum CRP higher in mixed infections involving influenza, but differences could not be achieved for PCT, probably due to low number of our cases (n = 15)." (PMID 25073709, 2014). "Similarly to the results of the present study the significant increase of Hp, but no CRP serum concentration were found in pigs with subclinical influenza." (PMID 24893655, 2014). "In assessing bacterial coinfection with influenza, PCT was superior to CRP, and PCT < 0.29 ng/mL had a high negative predictive value (NPV) of 94% for excluding coinfection, especially in patients without shock." (PMID 37638092, 2023). "Inflammatory markers including CRP, ferritin, LDH, D-Dimer were significantly higher at admission in the patients with influenza diagnosed with P-DM compared to those without P-DM." (PMID 36857969, 2023). "The influenza group showed lower PLT and platelet mass (PLT*MPV), and the non-influenza group showed significantly lower MPV, which was correlated with the vit D levels, but not CRP or ESR, and the value vit D*MPV was significantly lower in this group." (PMID 35463888, 2022). "The main results of this study are twofold: first, in patients with severe influenza infection, and in those with bacterial co-infection, initial PCT and CRP levels on ICU-admission were not factors independently associated with the prognosis." (PMID 33810263, 2021). "While our results do not suggest that influenza vaccination impacts RMR, they do corroborate prior research findings that influenza vaccination induces a mild acute inflammatory response that can be measured by CRP." (PMID 38100425, 2023).
influenza (continued). "The differences in platelet indices between the two groups with RTI, influenza and non-influenza, cannot be explained by the degree of inflammation as this was documented to be similar by the clinical symptoms and the levels of the inflammatory indices ESR and CRP." (PMID 35463888, 2022).
pancreatic cancer (155 papers, 2006 to 2026). "The analysis showed a correlation between an elevated risk of pancreatic cancer and genetically predicted pancreatic fat, high-density lipoprotein, BMI particles, BMI, fasting insulin level, Crohn illness, intestinal flora, and C-reactive protein." (PMID 39465831, 2024). "For example, a study in patients with unresectable pancreatic cancer or distal cholangiocarcinoma has shown that myosteatosis is associated with markers of systemic inflammation such as white blood cell count, CRP, and neutrophil‐lymphocyte ratio." (PMID 38725139, 2024). "Increased serum CRP levels have been associated with poor outcomes in most gastrointestinal malignancies, including pancreatic cancer." (PMID 37509622, 2023). "In a study of pancreatic cancer patients, levels of the inflammatory marker C-reactive protein (CRP) mediated the association between HRV and OS." (PMID 36523968, 2022). "While Phase II trial results in pancreatic cancer suggested an association between elevated CRP and response to ruxolitinib plus capecitabine, these findings were not seen in the Phase III trials." (PMID 33521321, 2020). "We found an increased risk of pancreatic cancer associated with pre-diagnostic serum levels of haptoglobin, CRP and leukocytes." (PMID 31464604, 2019). "We also observed a borderline significant positive association with risk of pancreatic cancer for those with higher levels of CRP (≥10 mg/L) compared to those with CRP levels < 10 mg/L [HR: 1.32 (95% CI 1.00–1.74)]." (PMID 31464604, 2019). "We found a borderline significant positive association between CRP and risk of pancreatic cancer, this finding is different from previous case-control studies about this association." (PMID 31464604, 2019). "We observed a positive association between haptoglobin, CRP and leukocytes and the risk of pancreatic cancer." (PMID 31464604, 2019). "In this study, by interrogating serum data from 61,597 healthy subjects in the AMORIS cohort with follow-up of 18 years, we found evidence for a positive association between serum haptoglobin, CRP and leukocytes, and the risk of developing pancreatic cancer." (PMID 31464604, 2019). "We found an increased risk of developing pancreatic cancer when participants have increased levels of haptoglobin, CRP and leukocytes, serum markers of inflammation." (PMID 31464604, 2019). "It was also found that in pancreatic cancer patients, there is an association of only elevated CRP levels with poor clinical outcomes (OR: 1.6, 95% CI: 1.16–2.21) in a multivariate analysis." (PMID 29619344, 2018). "In a meta-analysis, only three of six studies found low CRP levels to be associated with increased survival in pancreatic cancer." (PMID 29619344, 2018). "Elevated CRP levels (CRP > 10 mg/L), an indirect measure of systemic inflammation, has been associated with cachexia and poor prognosis in pancreatic cancer patients." (PMID 24624094, 2014). "Earlier, a similar association between elevated serum CRP concentrations and increased weight loss in pancreatic cancer patients has been identified and other groups have found similar associations in other cancer types." (PMID 19127266, 2009). "An elevation in CRP levels may increase the risk of developing pancreatic cancer in the future, as elevated levels of these biomarkers are associated with worse survival outcomes in patients with CP." (PMID 39568811, 2024). "In the univariate analyses, age, ECOG performance status, tumor staging, elevated CA 19-9 levels, hemoglobin levels, albumin levels, CRP levels, selected treatment modalities, and the presence of fatigue were significantly associated with the survival of pancreatic cancer." (PMID 39115263, 2024). "We utilised Kaplan−Meier survival curves based on the PF and CRP/Alb, and they showed that increased levels of these markers were associated with decreased OS in both the entire group of pancreatic carcinoma patients and specifically in those diagnosed with PDAC." (PMID 38496751, 2024).
pancreatic cancer (continued). "In addition, white blood cells and c-reactive protein can be elevated for several reasons and pancreatic cancer can be linked to pancreatitis." (PMID 36902776, 2023). "In this study, we evaluated associations between standard pre-diagnostic serum markers of chronic inflammation (CRP, albumin, haptoglobin and leukocytes) and pancreatic cancer risk in the Swedish Apolipoprotein-related MORtality RISk (AMORIS) prospective cohort study." (PMID 31464604, 2019). "CRP levels < 10 mg/L were unquantifiable, which may have resulted in an underestimation of the association with risk of pancreatic cancer." (PMID 31464604, 2019). "The current study aimed to evaluate associations between standard pre-diagnostic serum markers of chronic inflammation (CRP, albumin, haptoglobin and leukocytes) and pancreatic cancer risk in the prospective Swedish Apolipoprotein-related MORtality RISk (AMORIS) cohort study." (PMID 31464604, 2019). "In other cancer types, such as pancreatic cancer, it has been shown that the possession of a certain genotype results in an increased IL-1b production, which was associated with shortened survival and increased serum CRP level." (PMID 30647842, 2018). "Previous conclusive evidence has shown that the tumour-related inflammatory system is essential for tumour angiogenesis and tumorigenesis and that two parameters (fibrinogen and CRP/Alb) of inflammation-based biomarkers may be associated with the prognosis of pancreatic carcinoma." (PMID 38496751, 2024). "Studies have shown that in patients with rectal cancer, gastric cancer, and pancreatic cancer, the P-CRP value is a known synergistic prognostic indicator, which is more important than CRP or platelet levels alone." (PMID 39963109, 2025). "For instance, high BMI can mediate the occurrence of pancreatic cancer through C-reactive protein (CRP) as an intermediary factor." (PMID 40837436, 2025). "The protective role of the vagus in cancer is thought to be partly due to its anti-inflammatory effects, and this has been shown in pancreatic cancer, where lower C-reactive protein (CRP) significantly mediated the relations between HRV and longer survival." (PMID 40504312, 2025). "In contrast to CRP and cachexin levels, which have been more extensively studied in relation to the systemic immune response and pancreatic cancer prognosis, the role of MDW in long-term oncological outcomes remains largely unexplored." (PMID 41184833, 2025). "The CRP levels constitute important, promising inflammatory prognostic factors in pancreatic cancer." (PMID 39275204, 2024). "Contrastingly, the CRP/Alb ratio was demonstrated statistical significance in both the entire pancreatic carcinoma cohort (HR = 0.471; p = 0.026) and the PDAC subgroup (HR = 0.484; p = 0.034)." (PMID 38496751, 2024). "The findings revealed a positive correlation between the CRP/Alb ratio and PF (r = 0.489, p < 0.001) in all cases of pancreatic carcinoma." (PMID 38496751, 2024). "substantiated the CRP/albumin ratio’s role as a tool for predicting survival rates and gauging the effectiveness of chemotherapy in advanced pancreatic carcinoma." (PMID 38496751, 2024). "Nevertheless, there are still few publications describing the role of carnitines in pancreatic tumors and analysis of their correlations with clinical parameters of patients as a CRP marker or CA19-9." (PMID 37370852, 2023). "CRP/albumin ratio is used as a prognostic mediator for several cancers such as hepatocellular lung cancer, newly diagnosed pancreatic cancer, renal cancer or ovarian cancer." (PMID 37465171, 2023). "In patients with pancreatic cancer who underwent neoadjuvant chemoradiation therapy, CRP was increased and a value of greater than 10 kU/L was associated with reduced survival." (PMID 38022578, 2023).
pancreatic cancer (continued). "Regarding biological data, the patients with chronic pancreatitis showed higher serum values of amylase and lipase, while patients with pancreatic cancer had higher values of aminotransferases, cholestasis markers, CRP and uric acid." (PMID 36766475, 2023). "In pancreatic cancer patients, fibrinogen, D-dimer, and CRP values were significantly higher than in healthy controls." (PMID 37627058, 2023). "In the pancreatic cancer group, the total white blood cell counts increased, the neutrophil percentage increased, the lymphocyte percentage decreased, and the N/L ratio and CRP levels increased rapidly." (PMID 38143707, 2023). "In this study, even a small increase in the CRP values had a significant impact on the prognosis of patients with pancreatic cancer." (PMID 36766475, 2023). "We evaluated the systemic inflammatory syndrome through the values of the CRP and found it to be more elevated in patients with pancreatic cancer compared to those with chronic pancreatitis." (PMID 36766475, 2023). "More validation studies will be needed to confirm the relationship between certain treatment types and the utility of corresponding CRP level in pancreatic cancer." (PMID 37181043, 2023). "Second, whereas Glasgow and CRP-based prognostic assessment systems have been found to be helpful and important indicators of overall survival for pancreatic cancer, CRP wasn’t routinely evaluated in our patient population." (PMID 35722527, 2022). "In terms of pancreatic cancer, one of the widely described inflammation-based parameters is CRP/albumin ratio (CAR)." (PMID 35740504, 2022). "Ala Litman and coworkers explained the importance of the CXCL8-CXCR2 axis in pancreatic cancer, which indicate that the serum chemokine CXCL8 is a better diagnostic and predictive marker than CXCR2, C-reactive protein, classic CA 19-9, and CEA protein." (PMID 35468838, 2022). "In pancreatic cancer, it was found that the association between initial HRV and survival was statistically mediated by inflammatory biomarkers namely C-reactive protein." (PMID 36523968, 2022). "Pancreatic cancer patients with increased host immune response, measured by serum c-reactive protein (CRP) and isolated peripheral blood mononuclear cell cytokine production, had a higher REE than patients without an acute-phase response." (PMID 36072367, 2022). "CRP has been demonstrated to be inversely proportional to survival in a number of malignancies, including pancreatic cancer." (PMID 35939088, 2022). "In the present study, we observed the systemic activation of the complement system in patients with pancreatic cancer who were cachectic and who displayed a systemic inflammatory response as evidenced by elevated CRP levels." (PMID 34830921, 2021). "Using data from a previously published pancreatic cancer dataset, all three scores were moderately correlated with log CRP and log IL-6 levels." (PMID 34915912, 2021). "Numerous previous studies reported that inflammatory biomarkers, including C-reactive protein (CRP) and interleukin-6 (IL-6), were independently associated with overall survival in (from only 7 to 474) patients with pancreatic cancer." (PMID 34572824, 2021). "NAT patients with disease recurrence or death due to pancreatic cancer within 12 months postoperatively (n = 37) exhibited higher CRP (p = 0.002) and CA19-9 levels (p < 0.001) than patients with no recurrence." (PMID 33437015, 2021). "CRP is also reported to increase the malignant properties of pancreatic cancer cells through upregulation of the ERK/AKT/STAT3 pathway." (PMID 33801202, 2021). "Given these initial promising results, ruxolitinib was administered to patients with pancreatic cancer and an elevated CRP in two Phase III trials, JANUS 1 (NCT02117479) and JANUS 2 (NCT02119663)." (PMID 33521321, 2020).